IL22 (interleukin 22)
Diseases named in the same sentence as IL22 in open-access papers (continued):
Sharing a sentence is not in itself a finding about the gene and the disease.
infection (continued). "We measured Type 1 (IFN-γ, TNF-α, IL-2), Type 17 (IL-17, IL-22), and proinflammatory cytokines (IL-1α, IL-1β) in QuantiFERON (QFT) supernatants from TBI individuals with (TBI+Hel+) and without (TBI+Hel−) infection." (PMID 41583474, 2025). "Among the genes for T cell-mediated factors, the expression of genes for regulatory molecules such as IL-10 and IL-22 was increased by SCFA and infection, but that for other inflammatory molecules was not." (PMID 37865711, 2023). "Of note, while there was increased cell apoptosis by TUNEL staining in both Il-22−/− and Il-18−/− mice during AIEC infection, the percentage of Caspase-3+ UEA1+ Goblet cells was not increased in Il-18−/− mice." (PMID 35169117, 2022). "Infection by NTHi did not modulate the blood concentration of IFN-γ and IL-22 whereas it tended to increase the levels of IL-17 in CS-exposed mice." (PMID 33784296, 2021). "One study provided evidence that liver fluke infections can induce significantly higher IL-17A and IL-22 expression levels than healthy controls and CCA patients without an infection." (PMID 33851257, 2021). "HPX has recently been linked to host immunity and the anti-microbial action of IL-22 because, in mice, limiting infection depends upon HPX but not on Hp, in spite of the fact that the expression of both proteins in the liver is induced by IL-22." (PMID 31554244, 2019). "Whereas the secretion of IL-6 by spleen cells was unaffected by the lack of IL-22, the splenic production of IFN-γ, TNF and IL-10 was increased in IL-22−/− mice compared to wild-type mice at day 14 post infection." (PMID 27650379, 2016). "Il22 mRNA was expressed in spleens of C57BL/6, but not of IL-23p19−/− mice, 14 days after the infection, indicating that IL-22 is produced during T. cruzi infection in an IL-23-dependend manner." (PMID 27650379, 2016). "In conclusion, induction of a balanced Th1/Th17 response and production of key effector cytokines, such as IFNG, IL2, IL17, IL21, IL22 and IL23A was observed in animals that controlled infection, regardless of previous BCG-vaccination." (PMID 24505407, 2014). "On day 41, 71, and day 105 after infection the bacterial load in the lungs of L-22−/− mice did not significantly differ from lungs of C57BL/6 mice, showing that IL-22−/− mice controlled bacteria as well as C57BL/6 mice up to 105 days." (PMID 23460846, 2013). "Together, after infection with Mtb the cellular sources of this TH17 cytokine are not defined and the impact of IL-22 on protective immune responses is not clearly understood yet." (PMID 23460846, 2013). "Cytokines with a clear response to the infection and/or a different response in the vaccinated and non-vaccinated chickens included iNOS, IFNγ, IL17 and IL22." (PMID 22384225, 2012). "Furthermore, the absence of the IL-22 cytokine exacerbates lung inflammation, resulting in significantly elevated levels of IL-1β, TNF-α, and IL-12 during infection." (PMID 39635124, 2024). "Cytokine signaling of IL-1β, IL-23, IL-17A, CCL7, CXCL10, TRAIL, CD40L, and BAFF provides protection against acute WNV infection in mice; IL-10 and IL-22 aid in WNV pathogenicity; IL-6 and IL-12 had no apparent effect during infection; and CCL2, TNF-α, and FasL roles remain elusive." (PMID 36992514, 2023). "Furthermore, the levels of interleukin (IL)-2, IL-4, IL-6, IL-22, and interferon (IFN)-γ, but not that of tumor necrosis factor alpha (TNF-α), IL-10, and IL-9, increased to their highest levels at day 4 post-infection and decreased thereafter." (PMID 31711531, 2019). "Human metapneumovirus (hMPV) infection prevents the nuclear translocation of STAT3 in a cytokine-specific manner, as this was only observed following stimulation with IL-6 and not in case of interleukin 22 (IL-22)." (PMID 29543893, 2018). "However, bacterial loads in the lungs of IL-22−/− mice did not significantly differ from lungs of C57BL/6 mice at early and late time points of infection." (PMID 23460846, 2013).
infection (continued). "In the mutant strain infection, we noted that Th17-related cytokines (IL-17A, IL-22) and neutrophil-related chemokines (CCL2, CCL3, CXCL1, CXCL2) are significantly reduced at the early stage of infection, which might be related to the absence of melanin and defects in growth and germination." (PMID 35696422, 2022). "We observed that regardless of the infection state in SFB colonized eSPF mice, within small intestinal LPLs nearly 100% of IL-17A+IL-22- cells expressed CD44+ and lacked CD62L expression with around 70% of them expressing CCR6, which is in contrast to IL-17A-IL-22- cells." (PMID 34566952, 2021). "Interestingly, IL-22/IL-17 production by ILC3 isolated from the cLP of IEC-MyDON mice remained at similar basal levels to that observed in MyDOFF mice, indicating that the increased resistance of IEC-MyDON mice to infection is not a consequence of restored ILC3 function." (PMID 28520792, 2017).
tumor (347 papers, 2010 to 2026). "The effect of IL-22 on tumor growth was investigated by using an in vivo model of HCC: a significant increase in tumor volume was associated with enhanced phosphorylation of STAT3 as well as upregulation of cyclin D1." (PMID 40806452, 2025). "ILC3s, which express RORγt and produce IL-17 and IL-22, are implicated in tumor-promoting inflammation, particularly in the colon." (PMID 40872551, 2025). "In MIBC, the presence of IL-22+ Th cells within the tumor has been associated with poor prognosis and resistance to adjuvant chemotherapy (ACT)." (PMID 39325360, 2025). "In breast cancer, IL-22 produced by Th17 cells is associated with reduced tumor formation and a good prognosis." (PMID 39534095, 2024). "Patients facing higher rates of tumor-associated mortality also tend to exhibit higher levels of specific cytokines (e.g., IL-6, IL-17A, IL-22, and transforming growth factor-β (TGF-β))." (PMID 39267848, 2024). "The putative risks of chronic IL-22 therapy are predominantly a risk of hyperproliferation or tumor development in the intestine or skin." (PMID 38811532, 2024). "IL22 signaling has been implicated in increasing stemness, tumor proliferation, tumor migration and invasion, and anti-apoptotic resistance in multiple cancer types." (PMID 38339226, 2024). "Early investigations discovered that IL-22 polymorphisms were related to an increased risk of developing CRC, which was later confirmed in human CRC studies that IL-22 was significantly expressed in tumor tissue and associated with chemoresistance responses." (PMID 37122757, 2023). "Low expression of miR-150 is also associated with tumor invasion induced by CCL20 and IL22, which lowers anti-tumor immunity and protects stemness." (PMID 36831498, 2023). "So far, Th22 cells and their main signature, cytokine IL-22, have been associated with tumor progression in patients with hepatocellular carcinoma, colon cancer, lung cancer, gastric cancer, and ovarian cancer, among others." (PMID 36980536, 2023). "The IL-22 expression in tumors was a poor prognostic factor for OS, and along with tumor-IL-22R1, was positively associated with the infiltration of CD68-positive TAM, which together displayed the worst prognosis outcomes regarding both OS and RFS." (PMID 37835465, 2023). "When assessing the tumor burden in six-month-old mice, IL22-deficient mice indeed possessed significantly less tumor burden than the wild-type control ones, while IL22bp-deficient mice had significantly more tumors than C57BL/6 mice." (PMID 36551508, 2022). "Our study corroborates these findings by adding two further murine HCC models to the record, which show that IL22 deficiency indeed protects from tumor development in the liver." (PMID 36551508, 2022). "First, we saw a reduction in tumor resident Th22, a primary source of IL-22 that has been implicated in promoting growth and metastasis of various cancer types." (PMID 36142210, 2022). "Liver-specific IL-22 transgenic (IL-22TG) mice are resistant to concanavalin A-induced liver injury but are more susceptible to tumor development with limited influence on liver inflammation." (PMID 34944732, 2021). "On the other hand, IL‐17 and IL‐22 production by RORγt‐expressing Th17 T cells or Th17‐like ILCs are associated with tumor progression in several tumor models." (PMID 34496133, 2021). "The long-term risk of tumor growth needs to be counterbalanced, which is the likely role of the endogenous IL-22 antagonist IL-22BP that is constitutively expressed in many tissues." (PMID 33692792, 2021). "Interleukin (IL)‐22 is recognized as a tumor‐supporting cytokine and is implicated in the proliferation of multiple epithelial cancers." (PMID 31725949, 2020). "IL‐22 inactivation causes downregulation of epithelial‐to‐mesenchymal transition genes in tumor cells." (PMID 31725949, 2020).
tumor (continued). "In the 4T1 model, injection of IL-22 increased tumor size which was associated with increased proliferation of tumor cells as indicated by more Ki-67-positive cells." (PMID 32649314, 2020). "The results inspired the authors to investigate the mechanisms undergirding these findings, and they discovered that IL-22-mediated tumour stemness was associated with the methylation of H3K79 in three core cancer stemness genes: NANOG, SOX2 and Pou5F1." (PMID 32760201, 2020). "In patients with gastric cancer, dysregulation of circulating TH22 cell frequency and IL-22 expression levels have been demonstrated, and were associated with advanced tumor features and patient survival." (PMID 31637216, 2019). "Loss of IL-22 or IL-22 receptor on epithelial cells results in delayed tissue repair, exacerbated inflammation and tumor development when intestinal cells are exposed to carcinogens." (PMID 32010138, 2019). "Anti-tumor: NCR+ILC3s produce IL-22, TNFα, IL-8 and IL-2 to activate endothelial cells forming protective tumor-associated tertiary lymphoid structures." (PMID 32117199, 2019). "Interleukin-22 (IL-22) is a well-known tumor related inflammatory factor that is associated with variety of cancers." (PMID 29262587, 2017). "On the one hand, IL-22 deficiency can delay tissue repair, thereby sustaining inflammation and leading to tumor development." (PMID 28492497, 2017). "Conversely, given the protumoral role for T cell-expressed IL-22 in cancer, prolonged therapeutic administration IL-22 has the risk of promoting tumor development." (PMID 27303405, 2016). "The cytokine interleukin-22 (IL-22), which is produced by T cells and natural killer cells, is associated with tumorigenesis and tumor progression in cancers." (PMID 26598081, 2015). "Inflammatory Th17 cells and their associated cytokines (i.e., IL-17A, IL-17F, IL-21, IL-22, etc.)mediate tumor growth in two distinct ways – by driving angiogenesis and by suppressing antitumor immunity." (PMID 24987392, 2014). "In the present study, we aimed to establish the role of IL-22 in SCCs in both immune competent and transplant recipients and to evaluate the immune microenvironment for the numbers and polarization states of tumor-associated T cells." (PMID 23667456, 2013). "Elevated cytokines (IL-22, IL-6) in plasma and tumor tissue are associated with resistance to EGFR-TKI therapy.Targeting cytokines (IL-6, IL-8, TGF-β) combined with EGFR-TKIs may help overcome resistance in NSCLC." (PMID 40002883, 2025). "Levels of IL-22 in tumor tissues and blood are associated with chemoresistance and indicate a poor prognosis for patients having chemotherapy, so IL-22 may be a useful prognostic biomarker for CRC patients." (PMID 37176567, 2023). "Indeed, this model reproduced the initial findings, since IL22-deficient mice were once again protected from tumor development, while IL22bp-deficient mice developed significantly more tumors than the control mice." (PMID 36551508, 2022). "Apart from IL-22, IL-17 has also been linked to both roles protecting and promoting tumor growth." (PMID 36341381, 2022). "Moreover, the increase in IL-22 by Tc22 has been positively associated with pro-tumour activity since it is capable of inducing tumour growth in transplant-associated SSC patients." (PMID 35406451, 2022). "KRAS mutations can interact with the IL-22 pathway and enhance tumor cell proliferation." (PMID 36452508, 2022). "Furthermore, we evaluated the associations of Th22 cells and IL-22 with different tumor stages or grades of RCC to identify their potential predictive and prognostic importance." (PMID 33390778, 2021). "In addition to this, loss of IL-22 binding protein, a soluble decoy receptor neutralizing IL-22-driven cell activation, has been shown to increase epithelial cell proliferation and was associated with a higher tumor burden." (PMID 32010138, 2019).
tumor (continued). "Interestingly, both IL-22bp-deficient animals with elevated IL-22 and IL-22-deficient animals have increased tumor burden in colitis-associated cancer (CAC) model." (PMID 29967613, 2018). "Thus, our results establish a previously unappreciated mechanism by which the pro-inflammatory cytokine IL-22 facilitates aerobic glycolysis associated tumor progression." (PMID 28445985, 2017). "Continuous exposure to proliferative and antiapoptotic signals may drive cells to change phenotype and become cancerous as demonstrated in IL-22 transgenic mice where IL-22 primes the liver to be more susceptible to tumor development." (PMID 28373874, 2017). "Techniques to increase the concentration of IL-22 in lavage samples, such as the use of small volume lavage or lavage catheters placed near the tumor, may further increase the diagnostic sensitivity." (PMID 27388918, 2016). "IL-22 is also associated with tumorigenesis and tumor progression in cancers 18,19." (PMID 26598081, 2015). "This supports the hypothesis that IL-22 in the tumor microenvironment might drive SCC proliferation under high metabolic demand associated with tumor growth and diminished enrichment of the environment secondary to tissue necrosis." (PMID 23667456, 2013). "Although we could not detect IL-10R2+ blood cells in PBMCs of these tumour types (data not shown), IL-10R2+ cells might have increased in early tumorigenesis in each cancer, with IL-22 level being high in tumour tissue, and tumour-associated myeloid cells playing an important role." (PMID 38643339, 2024). "In addition to metastasis, IL-22 has been also associated to chemoresistance and tumour growth." (PMID 35406451, 2022). "We observed that infiltration by IL-22 immune cells is significantly associated with an increased 5-year survival rate, independently of known prognostic factors including age, sex, T stage, N stage, tumor grade, vascular invasion, tumor border configuration, and microsatellite stability." (PMID 34296212, 2021). "Moreover, in vivo CM model, IL22 treatment caused a significant increase in tumor size." (PMID 32201538, 2020). "Thus, the lack of RegIIIγ expression in polyps, even in the presence of IL-22, may cause impaired barrier functions and increased inflammation in ApcMin/Min polyps, which may contribute to tumour formation." (PMID 31770366, 2019). "Therefore, we sought to investigate IL-22 expression and the related molecules in human CC in order to further elucidate whether IL-22 acts as a tumor promoter and to investigate the underlying mechanisms of action." (PMID 23379788, 2013). "Restoring tumor-suppressive miRNAs (e.g., miR-26 and previously miR-150) or suppressing IL22/IL22RA disrupts this pathway, inhibits CTCL cell migration, and promotes apoptosis in vitro." (PMID 41614909, 2026). "In these reactions, the organism implements a defensive DNA repair system through the production of IL-22, which proves to be an anti-tumor cytokine." (PMID 41596472, 2026). "Interleukin 22 (IL-22) has been linked to chemotherapy resistance in CRC patients and promotes tumor formation in CRC mouse models." (PMID 40896696, 2025). "In the pathogenesis of this cancer, significant importance is attributed to interactions between tumour cells and the tumour microenvironment, in which soluble immune system mediators—cytokines—play a key role, including IL-21 and IL-22." (PMID 40729006, 2025). "Subsequent analysis revealed a robust positive correlation among the expressions of IL-22, IL-26, and IL-17A, with their corresponding receptors were notably elevated in the tumor samples." (PMID 40452847, 2025). "IL-22 can promote both the growth and invasiveness of cancer cells and exert anti-tumour effects by limiting the chronic inflammation that promotes carcinogenesis." (PMID 40729006, 2025).